CRP (C-reactive protein)
Diseases named in the same sentence as CRP in open-access papers (continued):
Sharing a sentence is not in itself a finding about the gene and the disease.
inflammation (continued). "One such factor is C-reactive protein (CRP), an indispensable biomarker for chronic systemic inflammation." (PMID 27177774, 2016). "On the other hand, chronic inflammation is known to be enhanced with healthy aging, and we found that inflammatory factors such as CRP, adiponectin, TNF-α, and IL-6 were elevated in SSCs." (PMID 26559536, 2015). "Inflammatory factors such as ICAM-1, VCAM-1, TNFα, IL-6, and CRP have key roles in mediating vascular inflammation and blocking RAAS negatively modulates the levels of these inflammatory molecules." (PMID 24804145, 2014). "Systemic inflammation (CRP) increased from 2.9±4.2 mg/l Pre-surgery to 84.3±35.0 mg/l at Day 2 (P<0.001)." (PMID 23614020, 2013). "Chronic systemic inflammation, including C-reactive protein (CRP), interleukin-6 (IL-6), and tumor necrosis factor-alpha (TNF-α), has been associated with childhood maltreatment, and systemic inflammation has been identified as a gestational risk factor for adverse neurodevelopment in offspring." (PMID 40920854, 2025). "Second, 4 of the 23 patients could be categorized as having unstable liver function (total bilirubin, aspartate aminotransferase, or ALAT greater than twice the normal limit), and 6 patients had signs of liver inflammation (a CRP level >5 mg/L)." (PMID 40632895, 2025). "High-sensitivity CRP may be more relevant in detecting subclinical chronic low-grade systemic inflammation, as it can detect a minimal increase in CRP levels." (PMID 40428013, 2025). "Leukocyte counts, C-reactive protein (CRP), interleukin-6 (IL-6), interleukin-10, and tumor necrosis factor-α (TNF-α) are the markers used in most studies that are determined to be associated with low-grade chronic inflammation." (PMID 40332421, 2025). "It seems that silent systemic inflammation may occur if we consider that participants with SQ CRP ≥ 10 mg/L were slightly younger but with a high probability of taking more medicines for chronic conditions." (PMID 40565981, 2025). "Factorial analysis of mixed data (FAMD) identified significant associations between micro/macroscopic changes in chronic inflammation and HFC (CC = 0.837); increased levels of CRP and microscopic acute inflammation (CC = 0.792); and clinical activity scores of ASDAS-CRP and BASDAI (CC = 0.914)." (PMID 39594257, 2024). "Hypersensitive C-reactive protein was completely normal during the initial disease onset and 1-week follow-up (13/15), with mild increases occurring in two patients with concomitant mild lung inflammation." (PMID 37079256, 2023). "Systemic inflammation may be observed by elevated CRP, as found in several cross-sectional studies among children and healthy adults; however, in the present study, cooking and candle exposure did not alter CRP levels in serum." (PMID 37430267, 2023). "Hs-CRP level as a parameter of chronic systemic inflammation decreased after surgery (P < 0.001)." (PMID 35733870, 2022). "Chronic inflammation increases the release of inflammatory cytokines such as interleukin-6 and tumor necrosis factor-a which are responsible for the synthesis of systemic inflammation markers such as C-reactive protein (CRP) and serum amyloid A (SAA)." (PMID 36326333, 2022). "Therefore, serum CRP levels are proven to be an indicator of synovial inflammation and related to radiological progression." (PMID 36494477, 2022). "All these data indicated that AEE could prevent lung inflammation during ALI in rats by decreasing CRP, MPO, and MIF in a dose-dependent manner." (PMID 35967416, 2022). "In addition, the traits of smoldering vascular inflammation were present long-term, as evidenced by the CRP and CCL28 levels." (PMID 36289630, 2022). "Only CRP (5.62) was upregulated during chronic hepatic inflammation." (PMID 34086835, 2021).
inflammation (continued). "Regarding CRP, our experiments indicate that CRP binding becomes less affected by EDTA when the concentration of CRP increases: NHS vs. inflammation serum and moreover patient 1 (<5 mg/L CRP) vs. 2 and 3 (>100 mg/L CRP) shows that elevated CRP decreases EDTA interference with the binding." (PMID 28900428, 2017). "Our study is the first to have reported CRP concentrations in the synovial fluid of dogs and the results support the possibility that synovial fluid CRP is a useful biomarker of joint inflammation and a useful monitor of response to anti-inflammatory treatment." (PMID 23452411, 2013). "Chronic inflammation, defined as a prolonged, low-grade inflammatory response that persists over time, is characterized by elevated levels of circulating pro-inflammatory markers such as C-reactive protein (CRP), interleukin-6 (IL-6), and tumor necrosis factor-alpha (TNF-α)." (PMID 39519418, 2024). "Elevated serum CRP over the study period that may be a reflection of active gut inflammation was associated with a lack of improvement in BMD (OR 0.8, CI: 0.68–0.93)." (PMID 39275145, 2024). "Except for Grave’s disease, on which data are few, CRP has been reported to be elevated in autoimmune thyroiditis, but it cannot be used as a sole biomarker, and hsCRP has been noted as being elevated in Hashimoto’s thyroiditis, highlighting a possible chronic systemic inflammation." (PMID 37873776, 2023). "In addition to pulmonary inflammation, there is also systemic inflammation with increased levels of fibrinogen, C-reactive protein (CRP), serum amyloid A (SAA), and pro-inflammatory cytokines tumor necrosis factor-alpha (TNF-α), interleukin-6 (IL-6), and IL-8 in the serum." (PMID 34681202, 2021). "Therefore, results from this study suggest that Smad3 may play an essential role in renal inflammation and fibrosis under high CRP conditions." (PMID 34671208, 2021). "CRP may also promote synovial inflammations via the CD32-p38 and NF-κB-dependent mechanisms." (PMID 32508836, 2020). "Systemic inflammation, characterized by elevated levels of cytokines such as interleukin-6 (IL-6), tumor necrosis factor-alpha (TNF-α), and C-reactive protein (CRP), plays a pivotal role in bridging these conditions." (PMID 40218134, 2025). "Previous research has shown that individuals with frailty exhibit elevated levels of inflammatory markers such as C-reactive protein (CRP), interleukin-1 beta (IL-1β), and IL-6, accompanied by chronic systemic inflammation and increased monocyte counts." (PMID 40697920, 2025). "Blood samples at admission showed mild systemic inflammation with a median leucocyte count of 11 × 109 cells/L (IQR 9–13 × 109 cells/L), and a median C-Reactive Protein (CRP) of 7 mg/L (IQR 3–18 mg/L)." (PMID 40029446, 2025). "Chronic inflammation, marked by high levels of IL-6, TNF-α, and C-reactive protein (CRP), creates a landscape ripe for thrombosis, transforming vascular health and priming atherosclerotic plaques for rupture." (PMID 39769374, 2024). "The occurrence of low-grade chronic inflammation in individuals with T2DM triggered an excessive secretion of inflammatory markers, including CRP, interleukin-6 (IL-6), TNF-α and monocyte chemokine 1(MCP-1)." (PMID 38528483, 2024). "Systemic inflammation in CKD is common and increased serum inflammatory biomarkers like C-reactive protein (CRP), inter-leukin-6 (IL-6) and tumour necrosis factor (TNF) are associated with CVD and all-cause mortality." (PMID 38638550, 2024). "Markers of systemic inflammation at admission were elevated (mean WBC count: 14.58 ± 2.55; mean CRP: 86 ± 30; mean PCT: 0.17 ± 0.08)." (PMID 34350202, 2021). "A dramatic improvement of skin and joint inflammation, measured by PASI and DLQI scores, was accompanied by significant improvements in CRP and ESR." (PMID 34207504, 2021).
inflammation (continued). "Serum levels of C-reactive protein (CRP), E-selectin, and ICAM-1 (circulating markers of vascular inflammation), which were higher in irradiated control IgG-treated mice than in non-irradiated mice, were also significantly reduced by Ab417 treatment." (PMID 34078883, 2021). "As pancreatic inflammation is the most important characteristic feature of AP and involves an excessive recruitment of leukocytes, the levels of WBC and CRP have a major role in AP." (PMID 32942753, 2020). "However, the inflammatory infiltrates as well as CK-MB and CRP blood levels increased significantly with increasing age in long-standing persistent/permanent AF and a moderate positive correlation was found between the extent of atrial inflammation and the CRP blood levels in both AF subtypes." (PMID 32072262, 2020). "Since the presence of bacteria in blood is generally associated with systemic inflammation, we investigated whether there were differences in the bacterial composition of patients with systemic inflammation (high CRP levels, n = 4) and patients without systemic inflammation (low CRP levels, n = 6)." (PMID 30800122, 2019). "Inflammation was measured by systemic inflammation assessed using C-reactive protein (CRP) levels and subclinical joint inflammation determined using magnetic resonance imaging (MRI) of hand and foot joints." (PMID 29724244, 2018). "Numerous studies have reported a positive correlation between HUA and inflammatory biomarkers, including CRP, TNF-α and N-methyl-D-aspartate, suggesting that uric acid may play a role in inflammation and subsequent inflammation-related diseases." (PMID 39980850, 2025). "Studies have shown that persistent short sleep can induce low-grade systemic inflammation, increasing levels of C-reactive protein, IL-6, and TNF-α in the blood, thereby exacerbating chronic systemic inflammation, particularly in older and frail individuals, and promoting the onset of frailty." (PMID 41468459, 2025). "In the present prospectively designed study, we demonstrated that FCP, which is very specific to intestinal inflammation, is not superior to CRP in predicting ER when the appropriate cut-off values were selected." (PMID 39451607, 2024). "Systemic chronic inflammation plays a pivotal role in the pathogenesis of CKD, driving research into the involvement of inflammatory markers in CKD progression, including C-reactive protein (CRP), interleukins, tumor necrosis factor, interferons, and chemokines." (PMID 39882264, 2024). "CRP levels within the three MSM groups exhibited a trend similar to that of sCD14; this provides additional evidence for the persistence of chronic gastrointestinal inflammation following HIV infection, despite the use of ART." (PMID 38831399, 2024). "CRP is a nonspecific marker of inflammation, whereas FC and SL reflect leukocyte trafficking in the gut and are specific to intestinal inflammation." (PMID 36773075, 2023). "Aging leads to increased levels of pro-inflammatory factors (especially CRP, TNF-α, and IL-6) in the blood, thereby inducing long-term chronic inflammation and decreased immune function, which is also a major factor for the increased chronic disease risk in the elderly." (PMID 36294194, 2022). "CRP can increase the expression of ROS and Ox-LDL and aggravate vascular inflammation." (PMID 34777534, 2021). "At week 12, the GMA-SS exposure induced pulmonary inflammation in both strains, without consistent changes in markers of systemic inflammation (CRP, MCP-1, IL-6 and TNFα)." (PMID 31924220, 2020). "The lack of CRP levels at follow-up also resulted in difficulty in the comparison of chronic vascular inflammation between the 2 groups." (PMID 24381515, 2013). "In this cohort there were no cases of overt systemic inflammation according to maternal CRP, nor were ferritin and transferrin concentrations significantly correlated with CRP." (PMID 16000177, 2005).
inflammation (continued). "The highest dose (400 mg/kg) demonstrated the strongest anti‐inflammatory effect, restoring CRP and ALP levels closer to those of the control group and the reference laxative (YOH, 2 mg/kg, b.w.), further supporting its potential in alleviating LOP‐induced intestinal inflammation." (PMID 40923672, 2025). "However, low-grade myocardial inflammation that is not reflected by systemic CRP levels cannot be excluded." (PMID 36824453, 2023). "Patients also had no inflammation disease, which will increase hs-CRP and HOMA-IR in the study." (PMID 36556950, 2022). "All include CNO typical patterns of bone inflammation or monofocal bone disease with histological features resembling chronic inflammation in the absence of malignancy, the absence of other signs severe systemic inflammation (such as fever, high CRP and/or ESR), and chronic disease courses." (PMID 32705386, 2020). "These include the lower prevalence of HLA B27 in IBDSpA compared to classic AS,46–48 the relative contra-indication of non-steroidal anti-inflammatory drugs (NSAIDs) in patients with IBD53 and the lack of specificity of elevated serum CRP, as it may be due to active intestinal inflammation, as well." (PMID 36127923, 2022). "It is worth noting that IL-6, TNF-α, IL-1β, and c-reactive protein (CRP) are mainly considered biomarkers of PAMPs-related acute inflammation, whereas ‘silent’ systemic chronic inflammation is characterized by no specific markers." (PMID 36902097, 2023). "Markers of chronic inflammation (e.g. LBP and CRP) as well as fecal calprotectin and fecal IgA were not significantly different between the groups." (PMID 29211757, 2017). "Beside CRP and FC, both serum parameters may be a reliable, non-invasive and easily available biomarkers to distinguish IBD patients with and without intestinal inflammation." (PMID 32470973, 2020).
heart disease (225 papers, 2005 to 2026). "This aligns with evidence that weight loss can lower CRP and improve blood pressure and cholesterol levels, thereby reducing the overall risk of heart disease." (PMID 41154955, 2025). "The long-term supplementation of PA is inversely correlated to CRP levels and has been suggested to reduce low-grade inflammation associated with early stages of heart disease." (PMID 40831047, 2025). "Leptin has been linked to increased levels of CRP in blood vessels, which is associated with a higher risk of heart disease, and there is a link between leptin and CRP." (PMID 40871683, 2025). "For example, individuals with intermediate risk for heart disease, as determined by traditional risk factors, can be further stratified based on their hs-CRP levels." (PMID 39273041, 2024). "High-frequency keywords in the field of IL-6 signaling pathway in mendelian randomization included mendelian randomization, interleukin-6, il-6, c-reactive protein, association, coronary-heart-disease, inflammation, instruments, risk, and so on." (PMID 38579070, 2024). "In the hypertensive group, age, DM, heart disease, smoking, glycemic control before admission, CRP, LDH, lymphocytes, and D-dimer were significantly associated with mortality." (PMID 36366507, 2022). "One population-based study found a strong association between elevated remnant cholesterol and increased C-reactive protein (a well-known marker of low-grade inflammation), as well as the risk of ischaemic heart disease." (PMID 35871064, 2022). "In multivariate Cox’s model #2, SII ≥ 395 (HR 2.95; 95% CI 1.49–6.39; p = 0.001), heart disease, CRP ≥ 0.5, pT4, and pN+ were identified as independent risk factors for poor OS." (PMID 34118953, 2021). "The elevation of C-reactive protein (CRP) levels in blood was recognized as a cardiac disease risk factor." (PMID 34771095, 2021). "C-reactive protein has been widely used to assess inflammatory status and has been found to be strongly associated with the risk and prognosis of cardiac diseases." (PMID 33169224, 2021). "In multivariate Cox’s model #1, Neut ≥ 3690 (HR 1.97; 95% CI 1.08–3.68; p = 0.027), heart disease, CRP ≥ 0.5, pT4, and pN+ were identified as independent risk factors for poor OS." (PMID 34118953, 2021). "C-reactive protein has been found to be strongly associated with the risk of heart disease while many SNPs that are associated with the C-reactive protein also seem to have pleiotropic effect on lipid traits." (PMID 34157017, 2021). "The quantification of the risk measured by the CRP level showed that three samples showed a high risk of heart disease." (PMID 30804931, 2019). "Regarding underlying heart disease, co-morbidities, medication, and blood concentration of leucocytes and c-reactive protein (CRP), several differences were found between HTx and HI group (pi ≤ 0.01)." (PMID 31614807, 2019). "The median CRP level was 2.1 (0.9–4.8) (average risk), however, 38.5% had levels greater than 3.0 mg/L, which is considered high risk for heart disease." (PMID 26938991, 2016). "Normalization of CRP levels in subjects at risk for heart disease is associated with a significantly lower number of cardiovascular events." (PMID 24485007, 2014). "Psychiatric disorder was significantly associated with higher age (p<0.0001), higher levels of C-reactive protein (p<0.05), and positive family history of heart disease (p<0.05)." (PMID 25007072, 2014). "They found that the risk of ischaemic heart disease and ischaemic cerebrovascular disease was increased by a factor of 1.6 and 1.2, respectively, in persons who had CRP levels above 3 mg/l, as compared with persons who had CRP levels below 1 mg mg/l." (PMID 24590770, 2014). "In contrast, using CRP as a risk factor for heart disease is confounded when the individual has a systemic inflammatory disease and it is generally recommended that this biomarker not be used in this subset of the population." (PMID 25568804, 2014).